UBE2O (ubiquitin conjugating enzyme E2 O)
Diseases named in the same sentence as UBE2O in open-access papers (continued):
Sharing a sentence is not in itself a finding about the gene and the disease.
cancer (continued). "The dysregulation of UBE2O and its clinical significance has been previously reported in several types of human cancers." (PMID 34790050, 2021). "Past studies of microarray-based gene expression have identified a high UBE2O expression rate in a variety of human cancer subsets." (PMID 34451875, 2021). "The TMA slides were incubated with antibodies against UBE2O, and the cores were scored by the pathologist blind to cancer results." (PMID 34451875, 2021). "Another database analyzing cancer patient survival rates shows the clinical significance of UBE2O overexpression." (PMID 34451875, 2021). "As a large E2 ubiquitin-conjugation enzyme, UBE2O displays both E2 and E3 activities, and UBE2O deregulation is involved in various types of human cancers." (PMID 31907353, 2020). "The results showed that UBE2O was significantly upregulated in cancer tissues compared with corresponding normal tissues." (PMID 31907353, 2020). "For example, whether UBE2O synergizes with classical cancer pathways such as PI3K/AKT and Wnt/β-catenin warrants further investigation." (PMID 40426910, 2025). "In addition to hematological diseases and cancers, UBE2O has been found to be involved in many other malignancies." (PMID 39272922, 2024). "Some studies suggest that UBE2O has a significant role in several cancers." (PMID 37373211, 2023). "UBE2O modulates cancer progression through the AMPKα2‐mTORC1‐HIF‐1α axis in cancer cells." (PMID 35615976, 2022). "Interestingly, UBE2O mediates the ubiquitination and degradation of various proteins in different types of cancer." (PMID 36443833, 2022). "Overexpression of UBE2O abrogated cancer-inhibitory effect of Arborinine." (PMID 36185617, 2022). "Hence, these results indicate that UBE2O is a new cancer therapeutic target, which modulates the AMPKα2-mTOR-HIF1α axis." (PMID 37533513, 2022). "Therefore, UBE2O can function as an oncogene that initiates cancer progression and removes important metabolic checkpoints that provoke pro-growth cellular metabolism." (PMID 34451875, 2021). "Furthermore, in mouse cancer models, the removal of UBE2O weakened the intra-tumoral vascularization and expression of neovascularization genes, including HIF1a targets." (PMID 34451875, 2021). "In a substantial proportion of human cancers, UBE2O expression could impact both neoplastic malignancies and clinical outcomes." (PMID 34451875, 2021). "Finally, the UBE2O gene in humans is located at a region of chromosome 17 that is amplified in many cancers." (PMID 33375416, 2020). "A molecular modeling analysis suggested that arborinine could bind directly to the active site of LSD1, and blocks downstream signaling activities, notably the expression of the ubiquitin-conjugating enzyme E2O (UBE2O), an important protein for cancer cell survival and proliferation." (PMID 36840175, 2023). "Interestingly, we found that SDPR induced PTRF secretion via exosomes, which revealed that the inhibition of SDPR may be another approach to regulating the secretion of exosome-related PTRF in cancer cells excepted UBE2O." (PMID 36443833, 2022). "Nevertheless, it is still unclear whether UBE2O plays an essential role in cancer radioresistance." (PMID 32901121, 2021). "The profile of expression of UBA1, UBE2C, UBE2T, UBE2O, and CCNF in BRCA seemed to support their involvement in cancer initiation and progression." (PMID 34201347, 2021). "It is recognized that ubiquitin conjugating enzyme 2O (UBE2O), which directly targets AMPK for ubiquitination and degradation, is intensified in human cancers." (PMID 34451875, 2021). "Hence, UBE2O may be a useful target for cancer therapeutics." (PMID 34199813, 2021). "Ubiquitin-conjugating enzyme E2 O (UBE2O), a member of the E2 family, functions as an oncogene in human cancers." (PMID 34790050, 2021). "It is recognised that UBE2O, which directly targets AMPK for ubiquitination and degradation, is intensified in human cancers." (PMID 34451875, 2021).
cancer (continued). "In vitro assays revealed that UBE2O promoted BC cell proliferation and epithelial–mesenchymal transformation (EMT) and endowed BC cells with cancer stemness properties (CSPs)." (PMID 31907353, 2020). "Functional assays proved that UBE2O promoted BC cell proliferation and epithelial–mesenchymal transformation (EMT) and conferred BC cells with cancer stemness properties (CSPs)." (PMID 31907353, 2020). "The UBE2O/AMPKα2/mTORC1 axis favors the transcriptional activity of the oncoprotein MYC, generating a positive feedback loop that promotes cancer cell proliferation and epithelial–mesenchymal transformation (EMT) and endows BC cells with cancer stemness properties." (PMID 39272922, 2024). "For instance, downregulation of gene coding for ubiquitin conjugating enzyme E2 O (UBE2O) impairs the tumorigenesis, moreover combined treatment of UBE2O inhibitors and AMPK agonists, such as metformin, has been suggested as promising treatment strategy for cancer already before." (PMID 31703101, 2019). "For a previous study, we performed an in-depth investigation of UBE2O and demonstrated that UBE2O could promote BC cell proliferation and epithelial–mesenchymal transformation (EMT) and endow BC cells with cancer stemness properties (CSPs) via the UBE2O/AMPKα2/mTORC1-MYC positive feedback loop." (PMID 34976998, 2021). "Furthermore, as a downstream target of the UBE2O/AMPK/mTOR pathway, MYC transcriptionally promotes UBE2O expression, thus constituting a positive feedback loop that promotes cell proliferation and epithelial–mesenchymal transformation (EMT) in many types of human cancers." (PMID 39272922, 2024).
infection (2 papers, 2025). The state of being infected such as from the introduction of a foreign agent such as serum, vaccine, antigenic substance or organism. "In the current study, we validated the interaction between UBE2O and HBc in an infection model." (PMID 40992660, 2025). "At 6 days post-infection, an interaction between HBc/capsids and UBE2O was confirmed." (PMID 40992660, 2025). "However, the difference in mycobacterial survival in UBE2O-KO and UBE2O[S82A] mutant macrophages at 48 hours after infection suggests that UBE2O-dependent bacterial survival is also mediated by unknown ferritin-independent mechanism(s)." (PMID 40309767, 2025).
metabolic disorders (2 papers, 2022 to 2025). "Exploring and elucidating regulatory mechanism of UBE2O may identify novel crucial molecular targets so as to pave therapeutic approaches for ubiquitination-associated metabolic disorders and diseases." (PMID 37533513, 2022). "Elucidating the functions of UBE2O may lead to identification of neoteric crucial molecular targets so as to pave therapeutic approaches for ubiquitination-associated metabolic disorders and diseases." (PMID 37533513, 2022). "Therefore, the UBE2O/AMPKα2 axis is an important regulator of metabolic homeostasis in skeletal muscle and a potential therapeutic target for diabetes and metabolic disorders." (PMID 40426910, 2025).
hematological malignancies (1 paper, 2024). "Although there is currently no data supporting the use of UBE2O as a prognostic marker or for predicting therapy response in solid tumors or hematological malignancies, the role of this enzyme suggests that it could potentially serve as a biomarker for therapy response in the future." (PMID 39272922, 2024).
UBE2O also shares sentences with these, for which no sentence is quoted: acute promyelocytic leukemia (1 paper); adenocarcinoma (1); autoimmune hepatitis (1); bladder cancer (1); blood cancer (1); colon cancer (1); head and neck cancer (1); Insulin resistance (1); lymphoma (1); monoclonal gammopathy of undetermined significance (1); myelodysplastic syndrome (1); non-small cell lung carcinoma (1); prostate tumors (1); T cell lymphoma (1); type 2 diabetes (1).